HIF1A (hypoxia inducible factor 1 subunit alpha)
Diseases named in the same sentence as HIF1A in open-access papers (continued):
Sharing a sentence is not in itself a finding about the gene and the disease.
glioblastoma (continued). "In addition, STAT3 was shown to be a positive regulator of HIF1α, VEGF, MMP-2 and TWIST in hypoxic glioblastoma and its suppression induced proliferation arrest and apoptosis in glioblastoma cells." (PMID 38654280, 2024). "Parkin regulates the expression of HIF-1α and HIF-3α in glioblastoma-derived cell lines in vitro." (PMID 39408813, 2024). "Targeting the NF-κB-FAT1 axis might inhibit the important tumor-promoting pathway in glioblastoma because FAT1 and NF-κB independently enhance protumorigenic inflammation and upregulate the expression of HIF-1α/EMT/stemness in tumors." (PMID 35368876, 2022). "Further, the reduced viability of U251 cells treated with MET was found to be related with the reduction of hypoxia-inducible factor (HIF-1α) and vascular endothelial growth factor (VEGF), key actors of glioblastoma angiogenesis, as well as with the inhibition of PI3K/mTOR axis." (PMID 35326565, 2022). "Thus, a positive correlation between p21 and HIF-1α enhances GLUT-1/lactate dehydrogenase A (LDHA) mediated glycolysis and exacerbates glioblastoma radioresistance." (PMID 36157351, 2022). "Since ID2 can prevent proteasomal degradation of HIF-2α in glioblastoma cells by binding to VHL protein present in the Cullin ring E3 ubiquitin ligase (CRL) complex, we examined whether ID2 could inhibit HIF-1α degradation in HSCs." (PMID 35775482, 2022). "Interestingly, in silico analysis of MCT4/SLC16A3 and HIF-1α/HIF1A expression in microdissected GBM tumor compartments obtained from the IVY Glioblastoma Atlas Project database revealed an expression gradient for both genes from the leading edge towards the tumor center in most tumor specimens." (PMID 33936203, 2021). "Under low oxygen conditions, HIF-1α acts to increase levels of a downstream target, Bcl-2 interacting protein 3 (BNIP3) in a process that promotes autophagy and increased cell survival in glioma (U87) and glioblastoma (T96G) cells." (PMID 33500708, 2021). "Application of HIF-1α siRNA to human TMZ-resistant glioblastoma cells did not trigger cell autophagy." (PMID 34136065, 2021). "Glioblastoma neurospheres exposed to a hypoxic environment show a 10-fold increased expression of PFKFB3, as well as upregulation of LDHA, pyruvate dehydrogenase kinase 1 (PDK1), and HK-2, via HIF-1α signaling, particularly within the necrotic core." (PMID 34831136, 2021). "Thus, CoCl2 can elevate levels of HIF-1α in human and mouse TMZ-resistant glioblastoma cells and induce intracellular hypoxic stress." (PMID 34136065, 2021). "In glioblastoma, miR-675-5p is necessary for maintaining hypoxic responses by controlling the HIF1α mRNA stability and, in CRC, it participates in tumor progression by regulating HIF1α-induced EMT (epithelial-mesenchymal transition)." (PMID 32481626, 2020). "However, glioblastoma cells not only induce SLC7A5 in response to hypoxia through HIF2α but also, the HIF1α isoform is involved in its expression." (PMID 33321829, 2020). "Previous study revealed that FAT1 positively correlated with multiply hypoxia related genes and it was a potent regulator of EMT both via or independent of HIF1a in glioblastoma." (PMID 32677981, 2020). "Our results demonstrate a build-up of HIF-1α following hypoxia, as well as an increase in VEGF expression, thus highlighting the role played by hypoxia in the regulation of VEGF expression in cancer and, more specifically, in glioblastoma." (PMID 31698752, 2019). "Also, crosstalk between HIF-1α and STAT3 was reported, in different tumor types, including glioblastoma." (PMID 30621209, 2019). "Epileptogenic GBMs correlate with decreased hypoxia/ HIF-1α/STAT5b signaling compared to glioblastomas that do not present with epilepsy." (PMID 30621209, 2019). "This suggests a feed-forward mechanism between MLL1 and HIF1α targets that sustains the hypoxic response in glioblastoma and consequently may promote TIC self-renewal and tumorigenicity for which hypoxia and HIF1α-mediated transcription are key drivers." (PMID 31632393, 2019).
glioblastoma (continued). "In vitro, they demonstrated that severe hypoxia induces the expression of FAT1 and that the depletion of endogenous FAT1 under hypoxia induces a decrease in HIF-1α, CAIX, GLUT1, VEGFA, MCT4, HK2, BNIP3, and REDD1, as well as a decrease in glioblastoma cell invasion." (PMID 31010154, 2019). "Wang found that by reducing HIF1A, the level of GLUT1 also decreased in human glioblastoma cells." (PMID 30217067, 2018). "In a summary, we found that Hif-1α directly promoted H19 expression through binding to the H19 promoter and indirectly through SP1-mediated H19 transcriptional activation under hypoxia in glioblastoma cells." (PMID 28327666, 2017). "A small subpopulation of HIF-1α+ quiescent stem-like tumor cells was found in glioblastomas but not in lower-grade astrocytomas." (PMID 26799577, 2016). "The biological importance of SOX2+ (or NANOG+) HIF-1α+ RNApII-S2P-/low tumor cells was also confirmed by our finding that these cells were found exclusively in glioblastoma tissues but not in grade II–III astrocytoma tissues." (PMID 26799577, 2016). "When a similar simulation was conducted for the U87 cell line, there was not a significant change in the glioblastoma volume when either the IGFBP2 to HIF1α or the IGFI to HIF1α connection was removed, see S5 Fig." (PMID 25884993, 2015). "We found that glioblastoma growth was highly sensitive to this new hypothesized interaction, IGFBP2 to HIF1α signaling." (PMID 25884993, 2015). "We also noticed that the transcription of key genes involved in inflammation, proliferation, angiogenesis and extracellular matrix remodelling (including MMP2, HIF1A, IL1B, IL1A, IL1R1, MMP2, VEGFA), processes vital to glioblastoma development, were down-regulated by RND3 knock-down." (PMID 26132659, 2015). "Additionally, in endothelial cells, the external supply of VEGF induced the expression of HIF-1α, an important regulator of VEGF in hypoxia; and in glioblastoma cells, VEGF induced its own expression via VEGFR-2." (PMID 23401656, 2013). "Necrotic foci and the pseudopalisading regions are hypoxic and are the main sites of HIF-1α and VEGF expression in glioblastoma, which may result in high expression of CXCR4." (PMID 22539956, 2012). "We show here that hypericin also induces enhanced degradation of hypoxia-inducible factor 1α (HIF-1α) in two human tumor cell lines, U87-MG glioblastoma and RCC-C2VHL−/− renal cell carcinoma and in the non-malignant ARPE19 retinal pigment epithelial cell line." (PMID 21949677, 2011). "However, in some tumors, e.g., human glioblastoma, expression of HIF-2α is particularly high and it plays a more important role than HIF-1α." (PMID 21925595, 2011). "Glioblastomas frequently show SCF and HIF‐1α expression at the perinecrotic tumor regions." (PMID 20030644, 2010). "In glioblastoma (GBM), PRMT3-mediated stabilization of HIF1α drives angiogenesis and glycolysis under hypoxic conditions." (PMID 41583428, 2025). "GPx1 expression was positively correlated with tumor grade, expression of HIF-1α (hypoxia-inducible factor-1α), HIF-1α target genes, and tetraspanin exosomal marker genes (CD9, CD63, CD81)-conversely, it was inversely correlated with the overall survival outcome in human glioblastoma specimens." (PMID 41009025, 2025). "In glioblastoma (GBM), hypoxia enhances CSCs-mediated immunosuppression by activating the STAT3 pathway and hypoxia-inducible factor-1 alpha (HIF-1α) and hindering T-cell activation." (PMID 38704599, 2024). "It inhibited tumor cell growth in tumor stem-like-cell-enriched cultures isolated from two human glioblastomas (GBM) through the suppression of glucose transporter 3 expression and inhibition of the p-AKT/HIF1α pathway." (PMID 38672652, 2024). "In addition to HIF-1α, inhibiting HIF-2α can also disrupt the hypoxia pathway in glioblastoma." (PMID 39329757, 2024).
glioblastoma (continued). "Since previous results obtained in glioblastoma (GBM) cells showed the important role of CMA and suggested HIF-1α as a potential therapeutic target, here we also assessed whether HIF-1α abrogation could permit the switch toward responsiveness of TMZ-resistant cells." (PMID 37407979, 2023). "In summary, increased expression of BCAT1 in glioblastoma cells with preexisting high levels of expression leads to a decrease in α-KG concentration, stabilization of HIF-1α, and increased cell proliferation and invasion mediated by HIF-1α-dependent expression of FOXM1." (PMID 37885806, 2023). "The present study revealed that hypoxia-inducible factor-1α (HIF-1α), induced even in non-hypoxic conditions by cell-to-cell contact, was a critical cue responsible for the malignant characteristics of glioblastoma multiforme (GBM) cells through Notch1 signaling." (PMID 36183290, 2022). "In addition, HIF1α had been reported to promote the expression of ZEB1 in hypoxia, and the HIF1α/ZEB1 axis enhanced cancer cells aggressiveness and distant metastasis in bladder cancer and glioblastoma." (PMID 35589690, 2022). "In summary, HIF1α and HIF2α regulate glioblastoma malignant progression through the EGFR–PI3K/AKT pathway via a positive feedback mechanism under the effects of Sox2 and Klf4, which provides a new tumour development model and strategy for glioblastoma treatment." (PMID 33762574, 2021). "However, the change of mRNA levels of HIF-1α was not obvious treated with TGF-β1 or MK-2206 in glioblastoma cells." (PMID 34257808, 2021). "Further analyses indicated an effect of enhancing the sensitivity of glioblastomas cells in radiotherapy by E. ulmoides flavonoid, which might refer to downregulating HIF-1α/MMP-2 pathway, as the data showed the expressions of HIF-1α and MMP-2 were further reduced after the combination treatment." (PMID 34362420, 2021). "We did not observe any downstream signalling events in HEK293T, COS-7 or HUVEC cells, indicating that the interaction between ADGRL4/ELTD1 and the JAK/STAT3/HIF-1α pathway is specific for glioblastoma or other cancer cell types and does not apply within endothelial cells." (PMID 33893326, 2021). "In addition, HIF-1α deletion in glioblastoma cells was shown to increase TET2 transcription and translation levels and further promote ascorba-induced and TET2-dependent 5hmC, suggesting that HIF-1α is involved in regulating TET2 expression and 5hmC levels in malignant cells." (PMID 33109235, 2020). "Hypoxia-inducible factor 1α (HIF1α) promotes the malignant progression of glioblastoma under hypoxic conditions, leading to a poor prognosis for patients with glioblastoma; however, none of the therapies targeting HIF1α in glioblastoma have successfully eradicated the tumour." (PMID 33208727, 2020). "In addition, hypermethylation of ANKDD1A in glioblastoma has been reported; this gene interacts with FIH1 and decreases HIF1-α stability to inhibit cell autophagy in a hypoxic microenvironment, but its function in pituitary adenoma or the significance of promoter methylation is still unclear." (PMID 31796052, 2019). "In this study, we demonstrated that the mechanism of H19 induction under hypoxia is partly accounted for by Hif-1α directly binding to the H19 promoter, a process that requires specific protein 1 (SP1) to be activated by Hif-1α, which enhances H19 transcriptional activation in glioblastoma cells." (PMID 28327666, 2017). "We focused on digitoxin in our glioblastoma studies because: 1) Unlike digoxin, digitoxin at a concentration achievable in human use was capable of inhibiting HIF-1α; 2) Digitoxin is a lipid soluble compound and likely able to penetrate the blood-brain-barrier." (PMID 28410215, 2017). "In contrast, SOX2+ HIF-1α+ RNApII-S2P-/low cells could neither be detected around small necroses with pseudopalisading of tumor cells, which is another type of necrosis in glioblastoma tissues, nor in the areas devoid of necrosis." (PMID 26799577, 2016).
glioblastoma (continued). "Thus, we speculate that SOX2+ HIF-1α+ RNApII-S2P-/low cells and HIF-2α+ cells might play different roles in the biology of glioblastoma." (PMID 26799577, 2016). "Thus, the up-regulation of HIF-1α itself is not sufficient for glioblastoma cells to obtain a higher tumorigenic capacity, and the additional induction of quiescence appears to be crucial for this raised tumorigenic capacity to occur." (PMID 26799577, 2016). "Furthermore, vascular proliferation and necrosis, common features of glioblastomas, were present in tumors derived from the β-gal and HIF2α(PP) cells but not the HIF1α(PP) cells." (PMID 25893706, 2015). "Having established a role for oxygen tension and HIF-1α in regulating AC133 in vitro, we wished to further address whether tumor development and AC133 expression were affected by the expansion of human glioblastoma cells under different oxygen tension culture conditions." (PMID 22134773, 2012). "The purpose of our investigation was to evaluate, in colon cancer and glioblastoma cell lines, whether HIPK2 might inhibit HIF-1α expression and activity in hypoxia-mimicking condition and sensitize chemoresistant tumor cells to adriamycin (ADR)-induced apoptosis." (PMID 19128456, 2009). "In addition, HIF1α is involved in the regulation of miR-210-3p, CXCR7, CXCR4, IDH1, C-Met, SF/HGF, the S100A4/NMIIA axis, NO, VEGF, BAG3, and TDO2, and influences various aspects of the glioblastoma biology such as angiogenesis, invasion, metabolism, and therapy resistance." (PMID 38893207, 2024). "The 67 NPM1/HIF‐1α‐dependent gene signature was highly expressed in three cancer types with elevated NPM1 expression, namely lymphoid neoplasm diffuse large B‐cell lymphoma (DLBC), glioblastoma multiforme (GBM), and thymoma (THYM)." (PMID 34388291, 2021). "Moreover, they found that HIF-1α may promote H19 expression by both directly binding to the H19 promoter and indirectly through SP1-mediated H19 transcriptional activation under hypoxia in glioblastoma cells." (PMID 33673376, 2021). "In addition, ANKDD1A decreases the half-life of HIF1α by upregulating FIH1, decreases glucose uptake and lactate production, inhibits glioblastoma multiforme (GBM) autophagy, and induces apoptosis in GBM cells under hypoxia." (PMID 30082910, 2019). "One driver of glioblastoma dissemination might be hypoxia through HIF-1α mediated up-regulation of SDF-1 and CXCR4 in GBM cells." (PMID 30622535, 2018). "Of particular importance, a HIF-1α inhibitor, 2-methoxyestradiol, showed a dose-dependent decrease in tumor growth and angiogenesis in a rat orthotopic brain tumor model, underscoring the importance of inhibiting HIF in Glioblastoma multiforme (GBM)." (PMID 24465898, 2014). "Indeed, it has been observed in T98G glioblastoma, HSC-3 oral squamous cell carcinoma and MCF-7 breast adenocarcinoma cells that hypoxic conditions lead to an ~31–48% decrease in lat1 mRNA expression and that the expression could be restored by using an siRNA knockdown of hif-1α." (PMID 39768156, 2024). "Using this approach, we identified HIF1A, STAT3 and SNAI2 (Slug) as the three most overexpressed migration-related transcription factors in human glioblastomas when compared to non-tumor brain." (PMID 20565806, 2010). "glioblastoma multiforme) and HIF-1α is also expressed in benign ulcer lesions, particularly in the healing state, we classified the group of HIF-1α expression as a negative/superficial and deep/diffuse/vascular invasion pattern." (PMID 18452596, 2008). "Semiquantitative RT-PCR revealed that HIF-1α is evenly expressed in normal brain and astrocytic tumor tissues and that there is no upregulation of HIF-1α mRNA in glioblastoma samples in comparison to low-grade astrocytomas." (PMID 17597534, 2007). "Our data did not reveal any correlation between hypoxia induced HIF-1α protein overexpression and GAPDH regulation on mRNA and protein level in vitro in human glioblastoma cell lines." (PMID 17597534, 2007).
glioblastoma (continued). "Glioblastoma (GBM) frequently activates hypoxia signaling even under normoxic conditions, yet the mechanism sustaining hypoxia-inducible factor-1α (HIF-1α) stability remains unclear." (PMID 42020378, 2026). "This study investigates whether Hypoxia-Inducible Factor 1 alpha (HIF1α) and Hypoxia-Inducible Factor 2 alpha (HIF2α) coordinately regulate insulin-like growth factor 1 receptor (IGF1R) expression, thereby influencing chemosensitivity in glioblastoma multiforme (GBM)." (PMID 40290443, 2025). "Thus, HIF-1α and HIF-2α act as adaptive mediators of hypoxia rather than resolving it, making them central to the malignant progression of glioblastoma." (PMID 41450919, 2025). "Moreover, we showed, in a preclinical glioblastoma model, an uptake of [64Cu][Cu(ATSM)] in regions with severe hypoxia but also at the periphery of the tumors where staining for pimonidazole, CA-IX and HIF-1α is negative." (PMID 38006431, 2023).